COMMD2 (COMM domain containing 2)
Description:
Scaffold protein in the commander complex that is essential for endosomal recycling of transmembrane cargos; the commander complex is composed of the CCC subcomplex and the retriever subcomplex. May modulate activity of cullin-RING E3 ubiquitin ligase (CRL) complexes. May down-regulate activation of NF-kappa-B.
Synonyms: HSPC042
Tractability: PROTAC: ubiquitination databases record sites on it; its protein half-life has been measured.
Gene: Protein-coding gene on chromosome 3 (149,734,667 to 149,752,495, reverse strand). Ensembl gene ENSG00000114744.
Subcellular location: Cytoplasm
Subcellular location (Human Protein Atlas): Vesicles
Pathways (Reactome):
Metabolism of proteins: Neddylation
Gene Ontology:
Molecular function: protein binding
Biological process: endocytic recycling
Cellular component: cytoplasm; protein-containing complex; endoplasmic reticulum membrane; endosome membrane
Genetic constraint (gnomAD): Loss-of-function variants: 17 observed, 15.72 expected, observed/expected ratio (o/e) 1.08, 90% interval 0.74 to 1.61. The upper end of that interval is the gene's LOEUF score, 1.61, which puts it in group 6 of 6, group 1 being the genes least tolerant of losing a copy. Missense variants: 158 observed, 168.22 expected, observed/expected ratio (o/e) 0.94, 90% interval 0.82 to 1.07. Synonymous variants: 75 observed, 68.98 expected, observed/expected ratio (o/e) 1.09, 90% interval 0.9 to 1.32.
Homologues: Orthologues: chimpanzee COMMD2 (99% identical), rabbit COMMD2 (97% identical), guinea pig COMMD2 (95% identical), pig COMMD2 (95% identical), mouse Commd2 (94% identical), rat Commd2 (93% identical), dog COMMD2 (88% identical), zebrafish commd2 (77% identical), tropical clawed frog commd2 (73% identical), macaque COMMD2 (71% identical), Drosophila melanogaster CG7168 (31% identical).
Diseases named in the same sentence as COMMD2 in open-access papers:
COMMD2 is named in the same sentence as 27 diseases in open-access papers, as found by Europe PMC text mining. Sharing a sentence is not in itself a finding about the gene and the disease. The quoted sentences say what the papers report.
bladder cancer (2 papers, 2022 to 2023). "COMMD2's pro‐cancer activities in bladder cancer cells and uterine corpus endometrial carcinoma cells have also been explored." (PMID 36205192, 2023). "Furthermore, the COMMD2 gene co‐expression network is constructed with GSEA analysis, displaying significant interaction of COMMD2 with E2F targets, G2‐M checkpoint, and mitotic spindle in bladder cancer (BLCA)." (PMID 36205192, 2023).
lung adenocarcinoma (2 papers, 2022 to 2023). A carcinoma that arises from the lung and is characterized by the presence of malignant glandular epithelial cells. "However, in breast cancer (BRCA), kidney chromophobe (KICH), lung adenocarcinoma (LUAD), prostate adenocarcinoma (PRAD) and thyroid cancer (THCA) tissues, COMMD2 expression was markedly lower than that in the corresponding normal samples." (PMID 35574298, 2022).
diffuse large B-cell lymphoma (1 paper, 2023). "TMB was found to be favorably connected with COMMD2 expression in CHOL, LUAD, BLCA, and GBM, but negatively in case of ESCA, mesothelioma (MESO), and diffuse large B‐cell lymphoma (DLBC)." (PMID 36205192, 2023).
Hepatitis (1 paper, 2022). Inflammation of the liver. "Additionally, high COMMD2 expression was significantly associated with an unfavorable OS for LIHC patients with microvascular invasion, patients who did not consume alcohol and patients without hepatitis." (PMID 35574298, 2022).
liver cancer (1 paper, 2023). An epithelial or non-epithelial malignant neoplasm that arises from the liver. "Moreover, COMMD2 expression is linked to tumor stage, immunotype, and molecular typing, which is in line with previous research on liver cancer." (PMID 36205192, 2023). "COMMD2 may take part in the progression of liver cancers and interact with the epithelial sodium channel (ENaC) to regulate sodium homeostasis and blood pressure." (PMID 36205192, 2023).
lung carcinoma (1 paper, 2021). "COMMD2 is the second member of the copper metabolism MURR1 domain protein family, in which COMMD1 inhibits GBM cell proliferation and promotes lung cancer cell apoptosis." (PMID 34781885, 2021).
lymph node metastasis (1 paper, 2022).
rectal adenocarcinoma (1 paper, 2023). "In rectal adenocarcinoma (READ), TGCT, STAD, UCEC, and BLCA, COMMD2 expression was positively correlated with MSI; however, COMMD2 had an adverse relationship with MSI in DLBC, KICH, and LUSC." (PMID 36205192, 2023).
uterine corpus endometrial carcinoma (1 paper, 2023). A endometrial carcinoma (disease) that involves the body of uterus. "Finally, RNA interference data showed suppression of COMMD2 prevented proliferation and migration of BLCA and uterine corpus endometrial carcinoma (UCEC) cells." (PMID 36205192, 2023).
tumor (5 papers, 2021 to 2025). "High COMMD2 expression is associated with tumor-induced activation of the immune response and immune infiltration in HCC." (PMID 41200507, 2025). "Based on COMMD2 expression and DNA methylation levels, we investigated the association between COMMD2 and the tumor stemness indices mRNAsi and mDNAsi." (PMID 36205192, 2023). "COMMD2/3/10 were associated with tumor-induced immune response activation and immune infiltration in HCC." (PMID 34493238, 2021). "Additionally, we discovered that COMMD2 expression was linked to tumor stemness, TMB, MSI, immune cell infiltration, immune‐checkpoint inhibitors, and drug sensitivity in pan‐cancer." (PMID 36205192, 2023). "High COMMD2 expression was associated with pathological tumor stage and metastasis." (PMID 35574298, 2022). "In addition, the expression of COMMD2/3/10 was associated with tumor-induced immune response activation and immune infiltration in HCC." (PMID 34493238, 2021). "The mechanism by which COMMD2 promotes tumor progression needs to be clarified further, including how COMMD2 influences human tumor occurrence and progression." (PMID 36205192, 2023). "We found that COMMD2 expression levels were high in various tumor cell lines based on the Cancer Cell Line Encyclopedia (CCLE) database." (PMID 36205192, 2023). "Since we have already found that the expression level of COMMD2 affects the prognosis and treatment of tumor patients, we would like to investigate the potential molecular biological processes of COMMD2." (PMID 36205192, 2023). "Second, the role of COMMD2 in tumor immune infiltration needs to be further confirmed in vitro or in vivo." (PMID 35574298, 2022). "Concerning tumor grade, upregulation of COMMD2 expression was observed in grade 1, grade 2, grade 3, and grade 4 tumors, and COMMD2 expression increased as the pathological grade increased." (PMID 35574298, 2022). "Taken together, our findings indicate that COMMD2 plays an important role in regulating the tumor infiltration of immune cells in HCC." (PMID 34493238, 2021). "The results revealed that the mRNA levels of COMMD2/3/10 were correlated with HCC tumor purity and immune infiltration levels in HCC (p < 0.05)." (PMID 34493238, 2021). "Additionally, COMMD2 impacts the overall survival of patients with HCC by enhancing tumor immune infiltration." (PMID 36776284, 2023). "All these findings suggested that COMMD2 is closely related to the level of immune infiltration, suggesting that COMMD2 may be involved in regulating LIHC tumor immunity." (PMID 35574298, 2022). "Furthermore, COMMD2 was significantly positively correlated with tumor immune cell infiltration, immune cell biomarkers, and immune checkpoint molecule expression." (PMID 35574298, 2022). "As Tregs play an important role in tumor immunosuppression, this may partly explain why COMMD2 is an oncogene." (PMID 34493238, 2021). "This suggests a role for COMMD2 in regulating tumor infiltration of Th cells." (PMID 34493238, 2021). "Thus, it may be stated that COMMD2 may play a essential role in regulating the responsiveness of tumor immunotherapy and targeted therapy." (PMID 36205192, 2023).
tumor (continued). "Moreover, COMMD2 was closely related to immune markers of these tumor-infiltrating immune cells." (PMID 35574298, 2022). "Additionally, our study showed that COMMD2 might play a cancer-promoting role by regulating tumor immune cell infiltration in patients with LIHC." (PMID 35574298, 2022). "In addition, COMMD2 expression was positively correlated with CD8+ T cells, macrophages, myeloid dendritic cells, and neutrophil‐infiltrated cells in numerous cancers, implying that COMMD2 had a impact on immune cell infiltration and may affect tumor immunotherapy." (PMID 36205192, 2023). "To further verify the relationship between COMMD2/3/10 and immune infiltration in HCC, we used the TIMER database to evaluate the correlations of these COMMD family members with tumor purity and the levels of infiltrating immune cells." (PMID 34493238, 2021). "This study showed that COMMD2 expression was higher in HCC tissues than in normal tissues and was correlated with tumor grade and individual cancer stage." (PMID 34493238, 2021). "Moreover, we validated that the expression of COMMD2 was upregulated in BLCA and UCEC tumor tissues compared with the normal tissue by performing IHC." (PMID 36205192, 2023). "In the present study, we first performed pancancer analysis of COMMD2 expression using the TIMER and UALCAN databases, and found that COMMD2 was abnormally expressed in the tumor tissues of 13 different cancer types compared with that in the corresponding normal tissues." (PMID 35574298, 2022). "Furthermore, we determined the correlations of COMMD2 with tumor-infiltrating immune cells, immune cell biomarkers, and immune checkpoint molecules in LIHC and analyzed the correlations between COMMD2 and infiltrating immune cells in the tumor microenvironment." (PMID 35574298, 2022).
cancer (4 papers, 2021 to 2025). A tumor composed of atypical neoplastic, often pleomorphic cells that invade other tissues. "The association between COMMD2 expression and prognosis was analyzed for various candidate types of cancer using the UALCAN database." (PMID 35574298, 2022). "Association analyses of COMMD2 with the survival of patients with candidate types of cancer indicated that high COMMD2 expression was associated with a poor prognosis in LIHC." (PMID 35574298, 2022). "While COMMD2, WSB2, and CUL9 have been implicated in various cancers, their roles in LSCC remain underexplored." (PMID 41200507, 2025). "Our findings shed light on the COMMD2 functions in human cancers and demonstrate that it is a promising prognostic biomarker and therapeutic target in pan‐cancer." (PMID 36205192, 2023). "The correlation between COMMD2 expression and immune and molecular subtypes of various cancers has been studied." (PMID 36205192, 2023). "The purpose of this study was to discover the expression of COMMD2 and its prognostic significance in pan‐cancer." (PMID 36205192, 2023). "Kaplan–Meier analysis (KM analysis) of COMMD2 in pan‐cancer was performed relying on the TCGA dataset." (PMID 36205192, 2023). "This study highlighted the value of COMMD2 in human tumors and demonstrated that COMMD2 is a promising prognostic biomarker and therapeutic target in pan‐ cancer." (PMID 36205192, 2023). "In this study, we first performed expression profiling and survival analysis of COMMD2 in various human cancers." (PMID 35574298, 2022). "Compared with that in normal tissues, COMMD2 expression was significantly higher in stage 1, stage 2, stage 3 and stage 4 cancers." (PMID 35574298, 2022). "The COMMD2 level was significantly related to the age of the patient and remarkably correlated with cancer stage." (PMID 35574298, 2022). "In conclusion, our findings add to our understanding of COMMD2's carcinogenic role, which could be employed as a prognostic biomarker and therapeutic target in pan‐cancer." (PMID 36205192, 2023). "Overall, this study offers comprehensive insight into the function of COMMD2 in human tumors and reveals that COMMD2 may serve as a useful prognostic biomarker and therapeutic target in pan‐cancer." (PMID 36205192, 2023). "For illustrating the relationship between COMMD2 and immune cell infiltration more comprehensively and accurately, various algorithms have been exploited to determine the relevance of COMMD2 expression and immune cell infiltration in diverse types of cancers." (PMID 36205192, 2023). "Although the COMMD family has been studied in human cancers, the expression and role of COMMD2 in tumors remains unknown." (PMID 36205192, 2023). "Furthermore, the MCPCOUNTER algorithm showed that neutrophil and endothelial cells were positively correlated with COMMD2 expression in most types of cancers." (PMID 36205192, 2023). "Furthermore, considering the small number of normal samples in TCGA, we combined TCGA with the GTEx database to further evaluate the differences in mRNA expression of COMMD2 in a broad manner in pan‐cancer." (PMID 36205192, 2023). "However, the expression, biological function, possible mechanism and prognostic relevance of COMMD2 and its correlation with immune cell infiltration in human cancers, including LIHC, remain unknown." (PMID 35574298, 2022). "To date, the expression or function of COMMD2 in human cancer remains unknown." (PMID 34493238, 2021). "We analyzed the expression profile of COMMD2 gene and ICGs (CD274, CTLA4, HAVCR2, LAG3, PDCD1, PDCD1LG2, SIGLEC15, and TIGIT) at a pan‐cancer level." (PMID 36205192, 2023). "COMMD2, WSB2 and CUL9 contribute significantly to many cancers or tumors." (PMID 41200507, 2025). "Furthermore, we investigated the relationships between COMMD2 expression and genomic alterations, TMB, MSI, and immune cell infiltrates in human cancers." (PMID 36205192, 2023).
COMMD2 also shares sentences with these, for which no sentence is quoted: cervical squamous cell carcinoma (2 papers); cholangiocarcinoma (2); esophageal cancer (2); lung squamous cell carcinoma (2); thyroid cancer (2); breast carcinoma (1); colon adenocarcinoma (1); colorectal adenocarcinoma (1); esophageal squamous cell carcinoma (1); glioblastoma (1); head and neck squamous cell carcinoma (1); hepatocellular carcinoma (1); mesothelioma (1); prostate adenocarcinoma (1); stomach adenocarcinoma (1); stomach cancer (1).